APOA4 (apolipoprotein A4)
Description:
May have a role in chylomicrons and VLDL secretion and catabolism. Required for efficient activation of lipoprotein lipase by ApoC-II; potent activator of LCAT. Apoa-IV is a major component of HDL and chylomicrons.
Synonyms: ADTKD6
Tractability: Antibody: its Gene Ontology location is reachable by antibodies, with high confidence; UniProt places it where antibodies can reach, with medium confidence; UniProt predicts a signal peptide or a membrane-spanning region. PROTAC: ubiquitination databases record sites on it; its protein half-life has been measured.
Gene: Protein-coding gene on chromosome 11 (116,820,700 to 116,823,304, reverse strand). Ensembl gene ENSG00000110244.
Subcellular location: Secreted
Subcellular location (Human Protein Atlas): Vesicles; Predicted to be secreted
Pathways (Reactome):
Transport of small molecules: Assembly of active LPL and LIPC lipase complexes; Chylomicron assembly; Chylomicron remodeling
Metabolism of proteins: Amyloid fiber formation
Sensory Perception: Retinoid metabolism and transport
Gene Ontology:
Molecular function: antioxidant activity; cholesterol transfer activity; copper ion binding; identical protein binding; lipid binding; phosphatidylcholine binding; phosphatidylcholine-sterol O-acyltransferase activator activity; protein binding; protein homodimerization activity; lipid transporter activity; phospholipid binding
Biological process: cholesterol efflux; cholesterol homeostasis; cholesterol metabolic process; chylomicron remodeling; high-density lipoprotein particle remodeling; hydrogen peroxide catabolic process; innate immune response in mucosa; leukocyte cell-cell adhesion; lipid catabolic process; lipid homeostasis; lipid transport; negative regulation of plasma lipoprotein oxidation; phosphatidylcholine metabolic process; phospholipid efflux; positive regulation of fatty acid biosynthetic process; positive regulation of triglyceride catabolic process; protein-lipid complex assembly; regulation of cholesterol transport; removal of superoxide radicals; response to lipid hydroperoxide; reverse cholesterol transport; very-low-density lipoprotein particle remodeling; acylglycerol homeostasis; chylomicron assembly; lipoprotein metabolic process; and 4 more
Cellular component: blood microparticle; cell surface; chylomicron; extracellular exosome; extracellular region; high-density lipoprotein particle; very-low-density lipoprotein particle; cytosol; early endosome; endoplasmic reticulum lumen; extracellular vesicle; low-density lipoprotein particle; synapse
Genetic constraint (gnomAD): Loss-of-function variants: 26 observed, 36.63 expected, observed/expected ratio (o/e) 0.71, 90% interval 0.52 to 0.99. The upper end of that interval is the gene's LOEUF score, 0.99, which puts it in group 4 of 6, group 1 being the genes least tolerant of losing a copy. Missense variants: 511 observed, 490.08 expected, observed/expected ratio (o/e) 1.04, 90% interval 0.97 to 1.12. Synonymous variants: 211 observed, 212.85 expected, observed/expected ratio (o/e) 0.99, 90% interval 0.88 to 1.11.
Gene-disease validity (ClinGen):
ClinGen rates the evidence that APOA4 causes each of these diseases.
autosomal dominant medullary cystic kidney disease with or without hyperuricemia (autosomal dominant): Limited. A genetic kidney disease that causes progressive loss of kidney function caused by mutations in the genes encoding uromodulin (UMOD), hepatocyte nuclear factor-1β (HNF1B), renin (REN), or mucin-1 (MUC1).
Homologues: Orthologues: chimpanzee APOA4 (98% identical), macaque APOA4 (94% identical), pig APOA4 (76% identical), rabbit APOA4 (71% identical), dog APOA4 (70% identical), guinea pig APOA4 (67% identical), rat Apoa4 (60% identical), mouse Apoa4 (60% identical), tropical clawed frog apoa4 (37% identical). Paralogues in human: APOA5 (22% identical), APOA1 (17% identical), APOE (15% identical).
Diseases named in the same sentence as APOA4 in open-access papers:
APOA4 is named in the same sentence as 176 diseases in open-access papers, as found by Europe PMC text mining. Sharing a sentence is not in itself a finding about the gene and the disease. The quoted sentences say what the papers report.
atherosclerosis (46 papers, 2009 to 2025). A disease characterized by the build-up of fatty material and calcium deposition in the arterial wall resulting in partial or complete occlusion of the arterial lumen. "APOA4 deficiency is associated with atherosclerosis and diabetes, which renders it as a potential therapeutic target for treatment of these diseases." (PMID 34441954, 2021). "APOA4 has been previously associated in humans and rodents with reduced extend of atherosclerosis and diabetes." (PMID 33949105, 2021). "Apolipoprotein A4 (ApoA4) is primarily expressed in the intestine and liver, reacts to fat absorption, and plays a role in regulating glucose homeostasis and lipid metabolism, thus reducing susceptibility to atherosclerosis." (PMID 38699158, 2024). "However, serum APOA4 concentrations are negatively associated with the presence and development of atherosclerosis in both HD (ESRD) patients and patients with mild to moderate renal failure." (PMID 34634315, 2021). "Conversely, APOA4 overexpression or recombinant APOA4 administration protects against HFD-induced atherosclerosis by lowering triglycerides, reducing vascular inflammation, and raising HDL cholesterol." (PMID 40723884, 2025). "ApoA4 is involved, among others, in lipid metabolism, reverse cholesterol transport, glucose metabolism, and protection against atherosclerosis, platelet aggregation, and thrombosis." (PMID 38732018, 2024). "Herein, the KEGG pathway enrichment analysis revealed that ApoA4 participates in several signaling pathways, including lipid and atherosclerosis, fat digestion and absorption, and cholesterol metabolism." (PMID 36714532, 2023). "APOA4 is involved in a myriad of physiological processes such as lipid absorption and metabolism, anti-atherosclerosis, platelet aggregation and thrombosis, glucose homeostasis and food intake." (PMID 34441954, 2021). "In summary, APOA4 can protect against lipid peroxidation, inhibit the progression of atherosclerosis, and enhance insulin secretion in OSA patients." (PMID 34185819, 2021). "In animal models circulating Apoa4 appear to confer some protection against diabetes and atherosclerosis." (PMID 34441954, 2021). "Apoa4 plays a role in reverse cholesterol transport and affords protection from atherosclerosis, and is also involved in fat absorption in the small intestine, the central regulation of food intake, and the regulation of insulin secretion from β-cells." (PMID 29738435, 2018). "This suggests that the suppression of the atherosclerosis pathway, induced by APOA4, may contribute to the improvement of FAO in this cluster of aged Tfebfl/fl KAP mice." (PMID 39699959, 2024). "In addition, previous research has confirmed that ApoA4 is involved in lipid uptake and metabolism and anti-atherosclerosis and inhibits thrombosis." (PMID 36714532, 2023). "APOA4, a lipid-binding protein, is known to be involved in a broad spectrum of biological processes, including lipid metabolism, reverse cholesterol transport, atherosclerosis protection, and glucose hemostasis." (PMID 35563307, 2022). "APOA4 is a lipid-binding protein synthesized in the small intestine, and is involved in numerous physiological processes, including lipid absorption and metabolism, platelet aggregation and thrombosis, anti-atherosclerosis, and glucose homeostasis." (PMID 35055195, 2022). "Given their protective functions against atherosclerosis and their yet unidentified roles in kidney disease, APOA4, LCAT, PON1, and PON3 may represent therapeutic targets for CVD in CKD patients." (PMID 34634315, 2021). "Importantly, overexpression of APOA4 protected against atherosclerosis in multiple studies with different strains of mice, likely by a mechanism that does not increase the concentration of HDL-C, suggesting that APOA4 by itself is antiatherogenic." (PMID 34634315, 2021).
atherosclerosis (continued). "Furthermore, transgenic overexpression of human or mouse Apoa4 conferred protection against atherosclerosis in mice." (PMID 29738435, 2018). "ApoA4, a protein expressed in the mammalian small intestine, appears to have various functions including playing a role as a lipoprotein anti-oxidant, participating in reverse cholesterol transport and being a major factor in the prevention of atherosclerosis." (PMID 29179490, 2017). "Since the SNPs at 11q23.3 region harbouring apolipoprotein coding genes namely APOA1, APOC3, APOA4, APOA5 and regulatory genes BUD13, ZPR1, SIK3 were found to be associated with defective lipid metabolism, this region was thought to play an important role in atherosclerosis and CAD risk." (PMID 33298998, 2020). "APOA4, a component of HDL, plays a critical role in lipid metabolism and reverse cholesterol transport and offers protection against atherosclerosis." (PMID 39513871, 2024). "Given APOA4’s wide range of functions, our findings may serve as the molecular basis for the development of APOA4-targeted therapeutics for diseases such as dyslipidemia, clinical complications of atherosclerosis, diabetes, obesity, Alzheimer’s disease, and other inflammatory conditions." (PMID 37092549, 2023). "In future studies, we will need to investigate the molecular mechanisms, whereby APOA4, LCAT, PON1, and PON3 protect against atherosclerosis in CKD and if improving their levels in HDL will reverse CKD atherosclerosis in model systems." (PMID 34634315, 2021). "Moreover, the rabbit model was more similar to developing human atherosclerosis when considering the expression change of APOA4 and APOB, thus making the rabbit a more suitable animal model to investigate human atherosclerosis." (PMID 39364866, 2025). "ApoA4, also known as Apoa-IV, is a lipid-binding protein and a component of HDL and chylomicrons with an active role in lipid absorption and metabolism, contributing to protection against diabetes and atherosclerosis." (PMID 34359627, 2021). "The expression change of APOA4 and APOB in human atherosclerosis was more similar to rabbit, and therefore rabbit might be a better animal model for investigating human lipoprotein metabolism related diseases." (PMID 30067832, 2018). "These roles of APOA4 in promoting reverse cholesterol transport and protecting LDL from oxidation may at least in part explain why human APOA4 transgenic mice have significantly reduced atherosclerosis compared with their wild-type counterparts." (PMID 37092549, 2023). "Additionally, compared to mouse, the primary responding molecules (APOA4 and APOB) had more similar expression change in high-fat fed rabbits and human atherosclerotic patients, suggesting rabbit is a better model to simulate the lipoprotein metabolism of human atherosclerosis." (PMID 30067832, 2018).
Obesity (40 papers, 2009 to 2025). Accumulation of substantial excess body fat. "Our results establish Apoa4 as a crucial regulator of lymphocyte metabolic and immune homeostasis in the early stages of obesity-associated CKD." (PMID 40999903, 2025). "Our data indicate that Apoa4, Ppap2b, Cel, and Clps are candidate early marker genes associated with obesity-related pathological changes in the colon." (PMID 27895803, 2016). "Apolipoprotein A5 (APOA5) gene, located on chromosome 11 adjacent to APOA1/APOC3/APOA4 gene cluster with known functions in the metabolism of plasma lipids, also modulates the risk of obesity in a number of studies." (PMID 24903888, 2014). "For example, polymorphisms in APOA4 have been associated with the risk of myocardial infarction in patients with obesity and type 2 diabetes." (PMID 19208189, 2009). "Our data demonstrate that Apoa4 deficiency exacerbates metabolic and immune disorders, highlighting its potential role in maintaining renal metabolic-immune homeostasis during early obesity-related CKD." (PMID 40999903, 2025). "RT-qPCR analysis revealed substantial alterations in the expressions of key regulatory genes governing glucose metabolism, lipid homeostasis, and mitochondrial function, collectively demonstrating that Apoa4 deficiency exacerbates obesity-induced renal metabolic dysregulation." (PMID 40999903, 2025). "Given that APOA1, APOC3, and APOA4 are genes associated with obesity and are grouped together in the same cluster as APOA5, it is possible that mutations in one gene within the cluster may be caused by genetic variations in another gene." (PMID 38867151, 2024). "APOA4 is markedly associated with obesity in mice, humans, and type 2 diabetes." (PMID 36614113, 2022). "In addition, APOA4 has an immune-regulatory role in some diseases, such as in alveolar macrophages, spondylarthritis, as well as obesity-associated inflammatory hepatic steatosis." (PMID 36614113, 2022). "Our data, combined with those of prior reports, suggest that Apoa4 deficiency may further aggravate metabolic dysfunction and oxidative stress, potentially dysregulating both pro- and anti-inflammatory responses in early obesity-related CKD." (PMID 40999903, 2025). "The effect of overexpression of intestinal APOA4 in the attenuation of HFD-induced obesity through modulation of lipid transport and metabolism in the small intestine, adipose tissues, and liver needs to be investigated." (PMID 36835642, 2023). "The next step will be to investigate the ability of continuous APOA4 infusion to attenuate potential obesity-related complications through the elevation of BAT thermogenesis and downregulation of hypertriglyceridemia in the face of a HFD challenge." (PMID 37299447, 2023). "Population-based cohorts showed that SNPs of ApoA4 gene lead to differential ApoA4 concentrations in plasma, which is related to obesity, T2DM, renal impairment in T2DM patients." (PMID 36426356, 2022). "This increased abundance is expected due to apolipoprotein A4 being involved in metabolic diseases such as obesity." (PMID 35745361, 2022). "APOC3 and APOA4 are two potential protein candidates of obesity cardiomyopathy signatures which levels were elevated in cardiac muscle and plasma but rescued after weight loss." (PMID 33716957, 2021). "Although all these apolipoprotein genes have been found to be related to obesity in at least one epidemiological study, only APOA4 has been subscribed in regulation of food intake, acting as a satiety signal." (PMID 24382995, 2013). "These ternary and quaternary relations (i.e. one gene, APOA4, and two conditions, obesity and type 2 diabetes, leading to another condition, myocardial infarction) are highly interesting to study, but we acknowledge will be missed by our current approach." (PMID 19208189, 2009).
Obesity (continued). "One speculated mechanism is that the effect of APOA5 gene variants on the risk of obesity might be attributed to this locus being in interaction with other obesity-risk genes, such as APOA1, APOC3 and APOA4 genes." (PMID 24903888, 2014). "Therefore, the decreased gene expression level of Apoa4 in the HF group could contribute to diet-induced obesity." (PMID 22715380, 2012). "BMI-predictive proteins included established obesity markers and obesity-related proteins, including adiponectin, CRP, IGFBP1, IGFBP2, PRG4, SHBG, apolipoproteins (APOA4, APOF) and inflammatory response proteins (A2M, APCS, LBP, HSPG2, HP, AOC3, ITGB1, VNN1)." (PMID 39972214, 2025). "APOA4 regulates BAT thermogenesis, lipid transport, glucose metabolism, cholesterol efflux, inflammation, and thrombosis, and protects against the development of atherosclerosis and obesity." (PMID 37299447, 2023). "APOA4 also plays important roles in modulating BAT thermogenesis, lipid transport, cholesterol efflux, inflammation, thrombosis, and processes that protect against developing atherosclerosis and obesity." (PMID 36835642, 2023). "Thus, overexpression of APOA4 in the small intestine and maintenance of elevated levels of plasma APOA4 appear to correlate with elevation of UCP1-dependent BAT thermogenesis and subsequent protection against HFD-induced obesity in mice." (PMID 36835642, 2023). "Maintenance of mouse APOA4 levels in the small intestine and plasma elevates UCP1-dependent BAT thermogenesis and energy expenditure and attenuates HFD-induced gains in body weight, fat mass, and plasma lipids, leading to protection against HFD-induced obesity in mice." (PMID 36835642, 2023). "APOA4 and APOC3 apolipoproteins were increased in the plasma of obese rats and four apolipoproteins were elevated in the heart (A1, APOA4, APOC3, and E), suggesting the high vulnerability of cardiac tissue toward the lipidomic changes accompanying diet-induced obesity." (PMID 33716957, 2021). "Considering both APOA4 and LRP1 are multifunctional players in lipid and glucose metabolism, our finding opens up a door to better understand the molecular mechanisms along APOA4-LRP1 axis, whose dysregulation leads to obesity, cardiovascular disease, and diabetes." (PMID 34168225, 2021). "Interesting, the expression of Apoa4 was up-regulated after SB addition which may alleviate the negative effect of high-fat diet induced obesity." (PMID 24852604, 2014).
diabetes (32 papers, 2008 to 2025). "Decreased circulating APOA4 concentration is associated with a higher risk of coronary artery disease and diabetes." (PMID 38044448, 2023). "Independent studies have implicated AMBP24, ApoA4, CRP, AHSG38 and HPX23 in DIO and diabetes." (PMID 32709962, 2020). "Furthermore, in the Fremantle Diabetes Study, ApoA4 has been identified as a novel plasma biomarker that predicts rapid decline in renal function independently of other clinical risk factors in T2D." (PMID 32830851, 2020). "Therefore, APOA4 and other apolipoprotein might participate in the pathogenesis of diabetes and diabetic complication." (PMID 26608305, 2015). "The mechanism of reduction of APOA4 expression in diabetes patients with pancreatic cancer was not investigated in this study." (PMID 38067270, 2023). "Furthermore, no justification was provided for the reduced levels of APOA4 in this subset of patients with diabetes." (PMID 38067270, 2023). "The present study revealed that APOA4 increased during CIH and OSA patients without atherosclerotic cardiovascular disease and diabetes mellitus and may be a potential marker for OSA complications." (PMID 34185819, 2021).